LGMNP1 (legumain pseudogene 1)
Synonyms: formerly LGMN2P
Gene: Processed pseudogene on chromosome 13 (64,958,097 to 64,959,396, reverse strand). Ensembl gene ENSG00000214269.
Diseases named in the same sentence as LGMNP1 in open-access papers:
LGMNP1 is named in the same sentence as 6 diseases in open-access papers, as found by Europe PMC text mining. Sharing a sentence is not in itself a finding about the gene and the disease. The quoted sentences say what the papers report.
glioblastoma (2 papers, 2020 to 2022). The most malignant astrocytic tumor (WHO grade IV). "The legumain pseudogene (LGMNP1) is overexpressed in glioblastoma cells resistant to radiotherapy and was shown to be functional in promoting tumor progression by acting as a microRNA (miR-495-3p)." (PMID 36555634, 2022). "Increased legumain expression by LGMNP1 is shown to be involved in tumor progression of glioblastoma." (PMID 36555634, 2022).
endometriosis (1 paper, 2022). The growth of functional endometrial tissue in anatomic sites outside the uterine body. "The characterization of endometriosis-specific exosomes such as miR-214-3p, extracellular vesicular Legumain pseudogene 1 (EV-LGMNP1) and actin filament associated protein 1-antisense RNA 1 (AFAP1-AS1) could open up new diagnostic and investigative pathways for treating endometriosis." (PMID 36210808, 2022).
ovarian endometriosis (1 paper, 2023). A non-neoplastic disorder characterized by the growth of endometrial tissue in the ovaries. "One recent study found that ectopic stromal cells collected from recurrent ovarian endometriosis patients induced anti-inflammatory polarisation of macrophages via the secretion of sEV-derived Legumain pseudogene 1 (EV-LGMNP1), a newly identified pseudogene of LGMN." (PMID 37077181, 2023).
LGMNP1 also shares sentences with these, for which no sentence is quoted: angle-closure glaucoma (1 paper); cataract (1); tumor (1).